PGM1 (phosphoglucomutase 1)
Diseases named in the same sentence as PGM1 in open-access papers (continued):
Sharing a sentence is not in itself a finding about the gene and the disease.
Alzheimer disease (1 paper, 2019). A progressive, neurodegenerative disease characterized by loss of function and death of nerve cells in several areas of the brain leading to loss of cognitive function such as memory and language. "These include phosphoglucomutase-1 (PGM1), reported to sustain cell growth during nutritional changes by regulating the balance between glucose-1-phosphate and glucose-6-phosphate and is differentially expressed in the brains of patients with Alzheimer’s disease." (PMID 31168311, 2019).
Autoimmunity (1 paper, 2023). The occurrence of an immune reaction against the organism's own cells or tissues. "Phosphoacetylglucosamine mutase (PGM3) is one of several paralogues (PGM1-3,5) that control glucose metabolism in most cells, and defects in PGM3 have been linked to autoimmunity." (PMID 38002248, 2023).
bladder cancer (1 paper, 2022). "In our study, PGM1 was significantly highly expressed in patients with high-grade bladder cancer, and its high expression seriously affected the prognosis of patients." (PMID 35251177, 2022).
cardiac arrest (1 paper, 2025). Cessation of breathing and/or cardiac function. "There are several reports of pediatric death in PGM1-CDG, and the leading cause of death in these patients was cardiac arrest." (PMID 40358162, 2025).
Cirrhosis (1 paper, 2018). A chronic disorder of the liver in which liver tissue becomes scarred and is partially replaced by regenerative nodules and fibrotic tissue resulting in loss of liver function. "Although altered glycogen metabolism commonly exists in various human cancers, the prognostic value of PGM1 in cancer has been rarely addressed except one study, which shows that PGM1 mRNA levels inversely correlate with human HCC and cirrhosis." (PMID 30335765, 2018).
colitis (1 paper, 2022). Inflammation of the colon. "Understanding how these sugars are transported and utilized becomes especially important since various diseases/disorders (LADII, GFUS-CDG, SLC35A2-CDG, PGM1-CDG, colitis, various cancers) are already using or exploring “monosaccharide therapy”." (PMID 36423686, 2022).
coloboma (1 paper, 2021). An abnormality in which a part of a structure in one or both eyes is missing. "These include: connective tissue involvement in ATP6AP1-CDG, midline malformations in PGM1-CDG, chronic diarrhoea in MPI-CDG, inverted nipples and abnormal fat distribution in PMM2-CDG, cataract/coloboma in SRD5A3-CDG, cerebellar hypoplasia in PMM2-CDG and SRD5A3-CDG." (PMID 33407696, 2021).
colorectal cancer (1 paper, 2022). A primary or metastatic malignant neoplasm that affects the colon or rectum. "Transwell assays were performed to evaluate the invasive and migratory capacities of colorectal cancer cells influenced by PGM1." (PMID 35614441, 2022).
colorectal tumor (1 paper, 2022). "A high level of PGM1 expression was observed in 41 normal tissues when compared to 471 colorectal tumor tissues (P < 0.0001)." (PMID 35614441, 2022).
cyst (1 paper, 2022). A sac-like closed membranous structure that may be empty or contain fluid or amorphous material. "Here, we used the CRISPR/Cas9 gene-editing system to disrupt pgm1 in a cyst-forming Toxoplasma strain." (PMID 35597992, 2022). "Together, our findings corroborate previous reports that PGM1 is dispensable for Toxoplasma viability and demonstrate that the enzyme contributes to optimal cyst development in vitro." (PMID 35597992, 2022). "Given the upregulation of pgm1 in chronic infection, we tested whether disruption of pgm1 would impede tissue cyst formation." (PMID 35597992, 2022). "Together, our results indicate that although PGM1 is not required for stage conversion and amylopectin storage, the enzyme contributes to optimal cyst development in vitro." (PMID 35597992, 2022). "In this study, we showed that disruption of pgm1 in a cyst-forming Toxoplasma strain did not prevent intracellular growth or completion of the lytic cycle in glucose-replete conditions, corroborating previous studies in non-cyst forming Type I tachyzoites." (PMID 35597992, 2022). "Overall, this study suggests that PGM1 is not critical for Toxoplasma growth and differentiation; however, it is required for optimal cyst maturation, which is critical for the establishment of chronic Toxoplasma infections." (PMID 35597992, 2022).
depression (1 paper, 2022). "Among them, except for PGM1, PMM2, and INMT, the expression of the other 7 proteins were significantly upregulated in susceptible mice, suggesting the potential role of these molecules in the pathogenesis of CSDS-induced depression in mice." (PMID 36291201, 2022).
endometrial cancer (1 paper, 1979). Primary or metastatic malignant neoplasm involving the endometrium (mucous membrane that lines the endometrial cavity). "Analysis of genetic variance for phosphoglucomutase at the PGM1 locus revealed a highly significant excess of the PGM1-1 phenotype in patients with cancer of the endometrium, which may reflect susceptibility to endometrial cancer in patients with this phenotype." (PMID 508567, 1979).
fungal infection (1 paper, 2021). "Apart from that, PGM1 gene was uniquely expressed under drought stress in vitro and overexpressed under Blumeria graminis fungal infection." (PMID 34961045, 2021).
glioma (1 paper, 2023). A benign or malignant brain and spinal cord tumor that arises from glial cells (astrocytes, oligodendrocytes, ependymal cells). "When the PGM1 expression is inhibited, glioma cells become less resistant to radio and chemotherapy." (PMID 38139462, 2023). "Moreover, the overexpression of PGM1 in glioma has been correlated with an increase in the DNA repair damage mechanism related to ATM." (PMID 38139462, 2023).
glycosylation disorders (1 paper, 2016). "Congenital deficiency of both PGM-1 and PGM-3 are associated with glycosylation disorders." (PMID 27707936, 2016).
Granuloma (1 paper, 2017). A compact, organized collection of mature mononuclear phagocytes, which may be but is not necessarily accompanied by accessory features such as necrosis. "Histologic examination of a pre-therapy lymph node biopsy specimen revealed non-caseating granulomas with sheets of CD1A−/CD207−/fascin+/CD163+/factorXIII−/PGM1+ histiocytes." (PMID 28512266, 2017).
hereditary angioedema (1 paper, 2022). Hereditary angioedema (HAE) is a genetic disease characterized by the occurrence of transitory and recurrent subcutaneous and/or submucosal edemas resulting in swelling and/or abdominal pain. "Top Reactome pathways enriched for the 65 unique proteins identified in the PSCs were pathways regulating striated muscle contraction, ARMS-mediated activation, defective PGM1, Factor XII, and SERPING1 casing hereditary angioedema, and in collagen degradation among others." (PMID 36002889, 2022).
hypothyroidism (1 paper, 2021). Abnormally low levels of thyroid hormone. "In this study, expression of pyruvate carboxykinase (Pklr), pyruvate carboxylase (Pc), glycogen phosphorylase (Pyg1), and Phosphoglucomutase-1 (Pgm1) were significantly down-regulated in hypothyroidism rats, which indicated that the glycolysis pathway was blocked." (PMID 33959028, 2021). "These DEPs including Pygl, Pklr, Pc, Ehhadh, Acox1, Fasn, Acly, Acsl1, Acsl5, Pgm1, Suclg1, Gpt, Idh1, Fh, and Adh1 maight be as target proteins of AMR and its fractions for hypothyroidism." (PMID 33959028, 2021).
infertile (1 paper, 2022). "Finally, six proteins were found to be unique in the infertile group; these were neuroblast differentiation-associated protein (AHNAK), isoaspartyl peptidase/L-asparaginase (ASRGL1), UMP-CMP kinase (CMPK1), phosphoglucomutase-1 (PGM1), cornulin (CRNN), and suprabasin (SBSN)." (PMID 35719135, 2022).
Insulin resistance (1 paper, 2022). Increased resistance towards insulin, that is, diminished effectiveness of insulin in reducing blood glucose levels. "The use of miR-124-3p to target PGM1 could be a novel and effective alternative for handling insulin resistance hence treating T2DM." (PMID 37529096, 2022).
Leigh syndrome (1 paper, 2025). A progressive neurological disease defined by specific neuropathological features associating brainstem and basal ganglia lesions. "Here, we present the first case with dual diagnosis of CDG and Leigh syndrome caused by (likely) pathogenic variants in PGM1 and NDUFA13." (PMID 40358162, 2025). "In conclusion, our results support the dual diagnosis of PGM1-CDG and Leigh syndrome caused by NDUFA13 deficiency." (PMID 40358162, 2025). "Proband’s clinical characteristics and their overlap with PGM1-CDG or NDUFA13/Leigh syndrome patients." (PMID 40358162, 2025). "Based on our results, the patient was diagnosed with both PGM1-CDG and Leigh syndrome." (PMID 40358162, 2025). "As nervous involvement is usually present in Leigh syndrome, but not in PGM1-CDG, one could speculate whether the differences in the lipid content in these two disorders could account for such different neurologic presentations." (PMID 40358162, 2025). "Finally, apart from confirming the patient’s diagnosis, the insights generated in this study could be critical for mapping disease mechanisms and treatment options in PGM1-CDG and Leighs syndrome patients." (PMID 40358162, 2025).
multinodular goiter (1 paper, 2019). Nodular goiter characterized by more than one discrete tissue mass. "The expression characteristics of 12 candidate reference genes (GAPDH, ACTB, HPRT1, TBP, B2M, PPIA, 18SrRNA, HMBS, GUSB, PGK1, RPLP0, and PGM1) were assessed by qRT-PCR in 45 thyroid tissue samples (15 papillary thyroid carcinoma, 15 paired normal tissues and 15 multinodular goiters)." (PMID 31645594, 2019).
Myalgia (1 paper, 2013). "Glycogen phosphorylase and phosphoglucomutase-1 were increased in cleaners with trapezius myalgia." (PMID 24023854, 2013).
neuroblastoma (1 paper, 2025). Neuroblastoma (NB) is the most common solid, extracranial childhood tumor. "The results revealed the presence of PGM1 in the cytoplasm, as determined by IHC staining analysis, and the high level of PGM1 expression was associated with poor overall and event-free survival in neuroblastoma patients." (PMID 40796729, 2025). "In this study, we first revealed that IRF6 acts as a potent inhibitor of tumor cell growth by targeting PGM1 transcription and modulating the cellular glycolytic process in neuroblastoma." (PMID 40796729, 2025). "Given the significant roles of IRF6 and PGM1 in glycolysis regulation and neuroblastoma progression, we analyzed their impact on patient survival in our cohort." (PMID 40796729, 2025). "In our study, we found that IRF6 directly interacted with the PGM1 promoter, inhibiting its transcription; subsequently, the downregulation of PGM1 inhibited glycolysis-mediated tumor cell proliferation in neuroblastoma, highlighting the role of PGM1 in facilitating the progression of neuroblastoma." (PMID 40796729, 2025). "Notably, neuroblastoma patients with PGM1 high/IRF6 low integrated expression had the worst overall and event-free survival." (PMID 40796729, 2025). "Interestingly, IRF6 targets the PGM1 promoter region and weakens its transcriptional activity in neuroblastoma." (PMID 40796729, 2025). "Our study revealed that PGM1 serves as a target for IRF6-mediated glycolysis and tumorigenesis in neuroblastoma cells." (PMID 40796729, 2025). "Clinically, neuroblastoma patients with PGM1 high/IRF6 low integrated expression had the worst overall and event-free survival, emphasizing the crucial role of the IRF6-PGM1 pathway in glycolysis-dependent tumorigenesis." (PMID 40796729, 2025).
steatosis (1 paper, 2021). Increased lipid within the cytoplasm of cells. "In two patients (SRD5A3-CDG and PGM1-CDG), apart from steatosis, mild inflammatory infiltrates were observed." (PMID 34291020, 2021).
xanthoma (1 paper, 2020). A non-neoplastic disorder characterized by a localized collection of histiocytes containing lipid. "Usually, the foamy cells in xanthomas show the marker CD68, a highly glycosylated, 110-kDa membrane protein that can be highlighted with monoclonal KP1 or PGM1 antibodies, yet has a weak cytoplasmic positivity with periodic acid–Schiff (PAS) staining." (PMID 32149048, 2020).
tumor (30 papers, 2011 to 2025). "To investigate whether PGM1-deficiency–promoted tumor cell proliferation requires glycolysis, we treated SK-Hep1 cells stably expressing shNT or shPGM1 with or without the glycolysis inhibitor 2-Deoxyglucose (2-DG)." (PMID 30335765, 2018). "A functional study revealed that PGM1 overexpression counteracts the inhibitory effects of IRF6 overexpression on glycolysis-mediated tumor cell growth." (PMID 40796729, 2025). "The interaction between tumor cells and CAFs induces phosphorylation and activation of PGM1, which promotes the transport of glycogen to glycolysis, leading to increased proliferation, invasion, and metastasis of tumor cells." (PMID 36994237, 2023). "We also demonstrated that a reduction of PGM1 levels in CRC cells stimulates both cellular proliferation and tumor growth by causing the cells to shift from glycogen synthesis and divert glucose to glycolytic pathways." (PMID 35614441, 2022). "PGM1 depletion reduces the glycogen content and the rates of glycogenolysis and glycogenesis, subsequently suppressing tumor cells proliferation." (PMID 36578780, 2022). "The low expression of PGM1 inhibited the glycogen synthesis pathway of tumor cells, making glucose more available for glycolysis, thus promoting tumor cell proliferation and the malignant progression of HCC." (PMID 35251177, 2022). "In order to assess the link between PGM1 levels and clinical characteristics, we collected tumor tissues and demographic data from 76 CRC patients." (PMID 35614441, 2022). "As verification, IHC staining was used to evaluate PGM1 protein levels in 100 CRC tissues on microarray chips, and the integrated optical density (IOD) for PGM1 expression in 100 tumor and normal samples was analyzed using GraphPad Prism software." (PMID 35614441, 2022). "The clinicopathological features were then analyzed and PGM1 expression was correlated with pathological tumor (pT) stage and pathological tumor node metastasis (pTNM) stage of GC patients." (PMID 34507580, 2021). "In the process of glycogen metabolism, the low expression of PGM1 hindered the glycogen synthesis pathway of tumor cells, making glucose more used in the glycolysis process, thereby promoting tumor cell proliferation and the malignant progression of HCC." (PMID 34194464, 2021). "Under the interaction between tumor cells and CAFs, p38αMAPK can induce the activation of phosphoglucomutase 1 in tumor cells, promoting glycolysis." (PMID 32786144, 2020). "Thus, we wondered whether loss of PGM1 promoted the invasive ability of tumor cells." (PMID 30335765, 2018). "We next examined the proliferation of these two PGM1-depleted cells, which showed that both shPGM1 and shPGM1-2 enhanced tumor cell proliferation in a depletion efficiency-dependent manner." (PMID 30335765, 2018). "Similar results were obtained in HepG2 cells, showing that depletion of PGM1 greatly enhanced glucose consumption and lactate production but decreased glycogen content of tumor cells." (PMID 30335765, 2018). "Semiquantitative analyses of IHC staining showed that PGM1 expression was much lower in tumor tissues than that in paired peritumoral tissues." (PMID 30335765, 2018). "On the contrary, PGM1 depletion in HCC cells promotes tumor cell proliferation and tumor growth by inhibiting glycogen synthesis to spare more glucose for glycolysis." (PMID 30335765, 2018). "The weights of dissected tumors showed that FOXJ2 overexpression greatly impaired tumor growth, while PGM1 depletion almost completely rescued the tumor growth inhibited by FOXJ2 overexpression." (PMID 30335765, 2018).